APOE (apolipoprotein E)
Diseases named in the same sentence as APOE in open-access papers (continued):
Sharing a sentence is not in itself a finding about the gene and the disease.
atherosclerosis (continued). "Moreover, in models of atherosclerosis, such as the apolipoprotein E (apoE−/−) mouse, resveratrol reverses endothelial nitric oxide synthase (eNOS) uncoupling and reduces oxidative stress." (PMID 29234485, 2017). "The present study aimed to determine whether the effect of Up4A on coronary flow is altered in atherosclerosis and to evaluate the possible role of purinergic receptor subtypes using Langendorff-perfused isolated hearts from the ApoE knockout (KO) mice." (PMID 28929376, 2017). "We next addressed whether the polyclonal antibody against M2FA recognizes atherosclerosis plaque in ApoE−/− mice." (PMID 28883613, 2017). "In line with our previous atherosclerosis studies, catK deficiency did not alter serum cholesterol level in neither apoE-/- nor wt mice (n = 14–15 for apoE-/- and catK-/-//apoE-/- mice; n = 7 for wt and catK-/- mice, S1 Fig)." (PMID 27636705, 2016). "Indeed, vascular smooth muscle-specific miR-143 expression was decreased in aortas of ApoE−/− mice in states of atherosclerosis and/or CKD during VC progression." (PMID 27419135, 2016). "In conclusion, repeated pulmonary exposure to nanosized CB and LPS caused lung inflammation without progression of atherosclerosis in ApoE-/- mice." (PMID 27571356, 2016). "In a recent unpublished animal study in apoE-KO mice, we found by 16S ribosomal RNA sequencing that 1.5 % supplementation of α-CD markedly changed the gut microbiome, which has been shown modulate atherosclerosis." (PMID 27405337, 2016). "It will be of interest to test the possibility whether the atherosclerosis immune response within the arterial wall may be altered by crossing ApoE−/− with PLVAP−/− mice that have a pathological conduit system." (PMID 27777573, 2016). "In addition, Lactobacillus-treated ApoE knockout (ApoE-/-) mice were used to examine factors that induce the progression of atherosclerosis such as serum cholesterol, infiltrated immune cells, and atherosclerotic markers." (PMID 27120199, 2016). "The present study was conducted to determine whether the cardiac glycoside lanatoside C affects the development of atherosclerosis in ApoE–/– mice." (PMID 26821916, 2016). "However, APOE is polymorphic in humans and plasma LDL cholesterol levels, hence atherosclerosis risks are strongly associated with the three common APOE isoforms, in the following order: APOE4, APOE3, and APOE2." (PMID 27207171, 2016). "Furthermore, the expression of IL-33 and its receptor ST2 in murine and human cells and tissue reduces atherosclerosis development in ApoE-/-mice." (PMID 27223112, 2016). "Moreover, in contrast to conventionally colonized ApoE–/– mice, the same transgenic animals housed under GF conditions developed severe atherosclerosis when fed a low cholesterol diet." (PMID 27714645, 2016). "Knockout of NCEH1 in ApoE‐deficient mice promoted the development of atherosclerosis without altering the serum lipid profile 95 suggesting the atheroprotective role of this enzyme." (PMID 26493158, 2016). "Since ApoE(−/−) mice spontaneously exhibit atherosclerosis despite the diet, the results indicated that the high levels of H19 expression found in these mice might contributed to the spontaneous development of atherosclerosis." (PMID 27698357, 2016). "Here, this effect was evaluated with experimental atherosclerosis model in ApoE-/- mice and HUVECs." (PMID 27891092, 2016). "Finally, ApoE−/− mice have also been used to generate other relevant mouse models of atherosclerosis through breeding strategies." (PMID 27618031, 2016).
atherosclerosis (continued). "We wonder if levels of active-AEP would increase in ApoE-KO mice with severe atherosclerosis, and whether 7,8-DHF could inhibit its pathological influence or not." (PMID 27965573, 2016). "We next examined the progression of atherosclerosis in ApoE−/−/Irak-M−/− mice." (PMID 27824038, 2016). "However, in ApoE−/− mice, atherosclerosis was most prominent in aortic root, brachiocephalic artery followed by the aortic arch and carotid artery branches." (PMID 27491335, 2016). "The atherosclerosis observed in ApoE KO was abolished in Cyp27a1/ApoE double knockout (DKO) mice." (PMID 28149711, 2016). "We show that ADAMTS4 expression increases in plaques as atherosclerosis progresses in ApoE−/− mice." (PMID 27491335, 2016). "In contrast, the combination of inflammatory arthritis and ApoE deficiency does not enhance atherosclerosis beyond the high level observed in non-arthritic ApoE−/− mice." (PMID 27287704, 2016). "However, the ApoE−/− mouse is a model of a rare disease in humans, named homozygous familial hypercholesterolemia, while the atherosclerosis induced by LDL accumulation is the most common pathological mechanism in humans." (PMID 27618031, 2016). "Consistent with these actions, our group has shown that OPG increases leukocyte adhesion to endothelial cells, that it increases TGF-beta-mediated fibrogenesis and proliferation in vascular smooth muscle cells, and that it increases atherosclerosis extension in diabetic ApoE−/− mice." (PMID 28070143, 2016). "Therefore, A5 has been effectively used for various molecular imaging strategies in preclinical atherosclerosis models including ApoE−/− mice, as well as in human cardiovascular disease." (PMID 27618031, 2016). "We established low shear stress model of atherosclerosis in apoE−/− mice and C57BL/6J mice." (PMID 28155719, 2016). "Taken together, TXL treatment could mitigate plaque formation at the initial stage of atherosclerosis and stabilize atherosclerotic plaques in apoE−/− mice." (PMID 26908443, 2016). "Additionally, one study found that when Nod1 ligand FK565 was administered to apolipoprotein E [Apoe] knockout mice, development of atherosclerosis was accelerated." (PMID 27936005, 2016). "C5a receptor antagonist inhibited the development of atherosclerosis in ApoE−/− mice." (PMID 27517153, 2016). "Because caspases are an unexplored yet attractive target to modulate apoptotic cell death in atherosclerosis, we chose to examine the impact of caspase-3 deletion on atherosclerosis by crossbreeding caspase-3 knockout (Casp3−/−) mice with ApoE knockout (ApoE−/−) mice." (PMID 27847551, 2016). "Similarly, endothelial cell-specific Insr-knockout mice (EIRKO) displayed accelerated atherosclerosis when crossed with apolipoprotein E (ApoE) null mice." (PMID 27514532, 2016). "Hence, an obvious increase in plasma ADAMTS4 protein was also observed as atherosclerosis progresses in ApoE−/− mice from 12-weeks old to 18-weeks old." (PMID 27491335, 2016). "At an age of 16 weeks hyperlipidemic ApoE−/− rats revealed decreased aortic distensibility, and impaired vasorelaxation, when fed with normal chow, thus providing a useful tool to study aortic compliance and vascular response at an atherosclerosis prone stage." (PMID 27277003, 2016). "In contrast, in a recent study, deficiency of IL-33 and ST2 did not affect development of atherosclerosis in ApoE-deficient mice." (PMID 27142573, 2016). "Although the underlying mechanisms seem to be different for short- and long-term BM-573 administration, a potentially additive mechanism could account for the beneficial effects of BM-573 in ApoE-KO mice at early stage of atherosclerosis." (PMID 27019366, 2016).
atherosclerosis (continued). "It is possible that hypoxanthine has a negative impact on lipid and atherosclerosis in cases where APOE is deficient such as for APOE4 carriers with dysfunctional APOE status." (PMID 27396856, 2016). "In addition, accelerated atherosclerosis progress has been found in apoE−/− mice by oral or intravenous inoculation of P. gingivalis or Fusobacterium nulceatum." (PMID 27386384, 2016). "Also, RAGE deletion or blockade [using a soluble AGE receptor (sRAGE)] suppressed the development of atherosclerotic lesions and stabilized established atherosclerosis in diabetic ApoE-/- mice." (PMID 26807573, 2016). "It is therefore possible that the promotion of atherosclerosis in ApoE−/−Ltbrfl/flTagln-cre mice is due to mechanisms other than via ATLO’s impact on the disease and that – under different conditions – ATLOs may even promote the disease." (PMID 27777573, 2016). "In addition, the ratio of PCE/NCE reveals that atherosclerosis, per se, yields a cytotoxic effect compared with WT mice (WT: 0.52 ± 0.01 vs. apoE−/−: 0.28 ± 0.03)." (PMID 27229150, 2016). "For insight into mechanisms for Sirt6 heterozygosity exacerbated atherosclerosis, we investigated blood pressure, serum glucose and lipid level and body weight in ApoE−/− mice and Sirt6+/−ApoE−/− mice, which were fed with Western diet for 16 weeks." (PMID 27045575, 2016). "The ApoE−/− is a widely used mouse model of atherosclerosis." (PMID 27774459, 2016). "DHT attenuated atherosclerosis in ApoE-/- mice through regulating LOX-1 expression." (PMID 27891092, 2016). "To assess whether 3-MA can affect atherosclerosis, we systemically administered 3-MA to apolipoprotein E (ApoE)−/− mice fed a HFD for 8 weeks and analyzed its effect on atherosclerosis." (PMID 27906187, 2016). "A progression of atherosclerosis was observed by OilRedO staining as a progressive increase of lesion area, stenosis and lipid deposits in aortic roots from 24-week-old ApoE−/− vs. 8-week-old ApoE−/− mice." (PMID 27905925, 2016). "Moreover, 111In-DOTA-belatacept accumulation in the aortas of ApoE KO animals was dependent on an atherosclerosis-promoting diet." (PMID 26728358, 2016). "Atherosclerosis plaques were formed in the aortic arch of ApoE-KO LD/DL mice." (PMID 27631008, 2016). "These mice have significantly increased atherosclerosis compared to control diet ApoE−/− mice." (PMID 26914991, 2016). "Mice in which the APOE gene is deleted are prone to developing atherosclerosis." (PMID 27755538, 2016). "C5a overexpression could accelerate the development of atherosclerosis in ApoE−/− mice by promoting macrophage recruitment, foam cell formation and inflammatory activation." (PMID 27517153, 2016). "Transfer of KLF10-deficient T-cells failed to suppress the development of atherosclerosis in apolipoprotein E knockout mice with high-fat diet." (PMID 27899146, 2016). "Here, we showed that AsIV alleviated the extent of atherosclerosis in aorta of apoE−/− mice." (PMID 26074989, 2015). "The results described herein show that the deficiency of the endogenous IL‐33/ST2‐axis does not impact the development of atherosclerosis in ApoE‐deficient mice." (PMID 26417439, 2015). "Furthermore, we examined the effects of VDR deletion on atherosclerotic lesion formation in the apoE-/- atherosclerosis model." (PMID 26322890, 2015). "Also, calcium channel blockers have been reported to suppress the progression of atherosclerosis in ApoE−/− mice." (PMID 25785279, 2015).
atherosclerosis (continued). "To investigate whether the CCR5-overexpressing EPC treatment improved the EC function in ApoE−/− mice, we examined plaque content of ECs and the level of the serum NO, a molecule with protective effects in atherosclerosis." (PMID 25889019, 2015). "It is necessary to consider the potential ligands of TLR4 under stress that may contribute to inflammation and atherosclerosis in CUMS apoE-/- mice." (PMID 25860573, 2015). "In summary, deficiency of the endogenously produced IL‐33 and its receptor ST2 does not impact the development of atherosclerosis in ApoE‐deficient mice." (PMID 26417439, 2015). "Thus, STZ-induced hyperglycaemia accelerated atherosclerosis process and vulnerability of atheromatous plaque in apoE−/− mice." (PMID 25661015, 2015). "Notably, deficiency of TLR4 in apolipoprotein E-deficient mice is associated with lower CCL2 serum levels, reduced atherosclerosis and macrophage infiltration." (PMID 26001902, 2015). "Based on the current study showing the successful generation of an apoE-floxed model, future studies will help to further define the tissue-specific function of apoE for lipid delivery, atherosclerosis, bone growth, energy homeostasis as well as cognitive function." (PMID 26695075, 2015). "We found that hepatic hMsrA expression ameliorated lipid metabolism dysfunction and reduced the progression of atherosclerosis in Western-diet-fed apoE−/− mice, through altering the expression of several genes involved in lipid metabolism and inflammation in the liver." (PMID 26318157, 2015). "To test this hypothesis, we crossed Pak1 knockout mice to atherosclerosis-prone ApoE−/− mice, to generate ApoE−/−:Pak1−/− mice." (PMID 26104863, 2015). "Finally, a direct effect on the vascular wall is also possible, as TLR4 has been evidenced in human and murine atherosclerotic plaques, and inhibition of TLR4 signaling pathway attenuated diet-induced atherosclerosis in ApoE−/− mice." (PMID 25873766, 2015). "We present the findings of our proof-of-efficacy animal study in ApoE-/- mice aimed to examine whether HCQ has beneficial effects on atherosclerosis and vascular disease in presence of a uremic state." (PMID 26414017, 2015). "Because MED could effectively inhibit ox-LDL-induced macrophage foam cell formation and activation in vitro, we assessed whether MED could suppress HFD-induced atherosclerosis in ApoE−/− mice." (PMID 26045945, 2015). "Therefore, astragaloside IV plays a role in atherosclerosis of high-fat diet apoE−/− mice by regulating blood lipids, CD40-CD40L system, and SDF-1/CXCR4 biological axis probably." (PMID 26074989, 2015). "Genetic ablation of Akt3 in ApoE−/− mice led to a 2-fold increase in atherosclerotic lesions, and bone marrow transplantation of Akt3−/−/ApoE−/− to ApoE−/− mice also resulted in a significant increase of atherosclerosis." (PMID 25929188, 2015). "After 8 weeks on a high-fat diet, but not on a normal chow diet, atherosclerosis in aorta was increased in ARKO females (+59% vs. control apoE-deficient mice with intact AR gene)." (PMID 25550469, 2015). "T cells are known to play an important role in the development of atherosclerosis and it is reasonable to assume that the reduced development of atherosclerosis in ApoE/mdx mice at least in part is explained by a lower T cell recruitment into lesion-prone arterial sites." (PMID 26345322, 2015). "We also examined the role of P2X7R in the progression of atherosclerosis in apoE−/− mice." (PMID 25761252, 2015). "In a study that involved Ins2+/Akita:apoE−/− mice which developed type 1 diabetes, hypercholesteremia, and atherosclerosis spontaneously, severe leptin deficiency was seen compared to nondiabetic Ins2+/+:apoE−/− mice." (PMID 26064110, 2015). "Studies recently have shown VW-PCs in the adventitia of ApoE-deficient mice and these progenitors contributed to experimental atherosclerosis and did not originate from the bone marrow." (PMID 25866513, 2015).
atherosclerosis (continued). "Thus, we focused our investigations on VCAM-1, and found that atherogenic concentrations of arsenic induced vascular endothelial VCAM-1 expression at lesion-prone sites in apoE-/- mice model of atherosclerosis." (PMID 26332580, 2015). "We hypothesized that the interference of TLR4/NF-κB can ameliorate CUMS-induced inflammation and atherosclerosis in apoE-/- mice." (PMID 25860573, 2015). "TLR4/NF-κB pathway may participate in CUMS-induced atherosclerosis through activation of proinflammatory cytokines in apoE-/- mice." (PMID 25860573, 2015). "We tested the hypothesis that BSN723T lowers serum triglycerides and cholesterol, and prevents the formation of atherosclerosis in apoE-/- mice fed a Western diet." (PMID 27683620, 2015). "The most significant finding of this current study is that MED could dramatically suppress atherosclerosis in ApoE−/− mice fed a high fat diet." (PMID 26045945, 2015). "In addition, IL-1βdeficiency decreases the severity of atherosclerosis in apolipoprotein E knockout mice." (PMID 25894557, 2015). "However, a significantly delayed progression of atherosclerosis was observed in the apoE−/− P2X7R−/− mice." (PMID 25761252, 2015). "Therefore, adiponectin reduced atherosclerosis in ApoE−/− mice, likely through reducing superoxide production and preserving NO destruction." (PMID 25395016, 2015). "Finally, we analysed the progress of the atherosclerosis process in ApoE−/− mice fed with apple peel supplemented diets for 20 weeks." (PMID 26075004, 2015). "The effects of astragaloside IV on atherosclerosis in high-fat diet apoE−/− mice may be through platelet activation and SDF-1/CXCR4 biological axis." (PMID 26074989, 2015). "In addition, en face evaluation of pinned-out aortas showed 56% more atherosclerosis in DKO→ApoE−/− mice versus ApoE−/−→ApoE−/− mice (P < 0.001)." (PMID 26059978, 2015). "Depletion of perlecan HS in ApoE-null mice significantly reduced atherosclerosis." (PMID 25528754, 2015). "Previous studies have shown that exercise reduces atherosclerosis in apoE-/- mice while the effects of exercise on plaque formation in the presence of CKD have remained unknown." (PMID 25799529, 2015). "Lack of hepatic lipase resulted in reduced atherosclerosis in apolipoprotein E- and lecithin:cholesterol acyltransferase-deficient mice." (PMID 26143381, 2015). "This study tests the hypothesis that BSN723T can prevent the development of hyperlipidemia and atherosclerosis in ApoE-/- knockout mice fed a Western (high fat, high cholesterol, and high sucrose) diet." (PMID 27683620, 2015). "In present study, we observed that FO+ALA-PS exerted better alleviative effect on atherosclerosis in apoE KO mice than single treatment of flaxseed oil, and the underlying molecular mechanisms were related to lipid metabolism, inflammation, and oxidative stress improvement." (PMID 26180602, 2015). "Water restriction also caused slight but significant increase in serum cholesterol, which might be an additional factor contributing to the acceleration of development of atherosclerosis in water restricted ApoE-/- mice." (PMID 26042828, 2015). "The cell proliferation and migration of AFs derived from apoE(-/-) mice were significantly inhibited, further suggesting that p47phox may promote the formation of atherosclerosis through participation in the O2− generation." (PMID 25628043, 2015). "However, in a previous study, chronic unpredictable stress accelerated atherosclerosis by increasing serum levels of CRP in apolipoprotein E knockout mice." (PMID 25189624, 2014). "A recent epidemiological study reported that in the older persons, the association between APOE allele and CHD seems inconsistent, even though APOE alleles clearly influence plasma LDL-C and may be linked to atherosclerosis." (PMID 25333200, 2014).